MIR4499 (microRNA 4499)
Synonyms: hsa-mir-4499
Gene: MicroRNA gene on chromosome 13 (20,433,778 to 20,433,846, reverse strand). Ensembl gene ENSG00000263978.
Homologues: Orthologues: chimpanzee MIR4499 (100% identical).